C3 (complement C3)
Diseases named in the same sentence as C3 in open-access papers (continued):
Sharing a sentence is not in itself a finding about the gene and the disease.
Obesity (continued). "Plasminogen activator inhibitor-1 (PAI-1) showed an increase (p < 0.001), C3, an immune marker was significantly decreased (p < 0.01) and resistin, an adipokine involved in obesity and Type-2 diabetes, was also significantly decreased (p < 0.05)." (PMID 33383677, 2020). "Research shows that serum complement C3 has a significant correlation with obesity and also high gene expression complement C3 is observed in abdominal adipose tissue." (PMID 29299442, 2017). "A similar correlation between complement C3 and IR has been demonstrated in patients with Pso, polycystic ovary syndrome and obesity." (PMID 27656896, 2016). "Studies in humans have demonstrated that C3, the most abundant component of the complement cascade, and its mediator molecules are increased in obesity, metabolic syndrome and cardiovascular disease." (PMID 24743347, 2014). "Since there has been increasing interest in C3 cleavage products such as C3adesarg (ASP), which has been linked to obesity, we measured weight gain in our study." (PMID 24667818, 2014). "Higher levels of complement C3 were found here in PCOS and have been reported previously, which may reflect an association with the higher risk of obesity and atherosclerosis." (PMID 36980195, 2023). "A mechanistic role of adipsin in the development of obesity and T2D could be related to its function in regulating factors of the complement system, most importantly C3." (PMID 35216336, 2022). "Elevated levels of C3 and/or C3 cleavage products in the bloodstream were described in numerous pathologies, including autoimmune, neurological, renal, and cardiovascular diseases, cancer, transplant rejection, and obesity." (PMID 36558394, 2022). "Importantly, serum C3 level is considered as a pro-inflammatory biomarker contributing to low-grade inflammation and insulin resistance in obesity." (PMID 36248852, 2022). "This study aims to examine the relationship between adiposity, thyroid hormone levels and immunity by comparing resting energy expenditure (REE), serum thyroid hormone levels and complement C3 in normal-weight high body fat (normal weight obesity) women and normal-weight normal body fat women." (PMID 31666810, 2019). "We speculate that, in spite of a down-regulation of SC C3 gene expression, the large increase in SC adipose tissue mass in obesity might counteract this effect and contribute to the increased circulating C3 levels." (PMID 24743347, 2014). "We hypothesized that C3aR expression, its ligand; circulating C3a, and gene expression of the precursor complement C3 might be regulated in adipose tissue in relation to obesity." (PMID 24743347, 2014). "The obesity-induced down-regulation of complement C3 and C3aR which is specific to subcutaneous adipose tissue, coupled to the strong correlations with multiple anthropometric, plasma and adipokine variables support a potential role for complement in immunometabolism." (PMID 24743347, 2014). "Additionally, obesity itself is currently recognized as a potential risk factor for IBS, with clinical studies finding a positive correlation between body mass index and the levels of complement C3 and C-reactive protein in IBS patients." (PMID 40797420, 2025). "Increased C3 abundance was found increased in 2 independent studies of the present systematic review comparing EVs and plasma of individuals with obesity and lean controls and revealing the role of C3 in as an early marker for obesity and some related cardiovascular diseases." (PMID 38703299, 2024). "C3 and CRP may be useful clinical biomarkers of risk or treatment targets in women with obesity." (PMID 35306495, 2022). "In concrete, proteomic analysis revealed higher abundance of four complement system proteins—C3, C4b, C8, and CFH, in cats with obesity." (PMID 39795034, 2025). "In the present study, C3 levels were higher in the newly diagnosed T2DM group than in the other two groups, and higher in the obesity group than in the control group." (PMID 40487757, 2025).
Obesity (continued). "Interestingly, the association of complement factors (C3 and CFH) with anthropometric traits may reflect the low level inflammation induced by higher body mass, both of which associate with obesity, cardiovascular diseases, and increased susceptibility to infections." (PMID 35264221, 2022). "Elevated complement pathway proteins for both the classical and alternate cascades, including C3, C4, properdin, factor B and factor D, have been reported in PCOS, although their expression was correlated to obesity and insulin resistance." (PMID 36293087, 2022). "For example, in 97 patients with obesity underwent either RYGB or biliopancreatic diversion with duodenal switch, decreased levels of IFN-γ, hs-CRP, TNF-α, IL-13, IL-6, IL-1ra, C3, and leptin were described compared with baseline levels at 1-year follow-up55." (PMID 34108550, 2021). "However, whether the association between serum complement C3 levels or NAFLD is independent of obesity and metabolic syndrome remains not certain, neither is the link between serum C3 levels and severity of NAFLD." (PMID 27029598, 2016). "In relation to metabolic effects, an obesogenic diet induces increased liver expression of C3, C5aR, and C5L2, while C3KO, C5aRKO, C5L2KO, and C3aRKO mice are resistant to diet-induced obesity." (PMID 24796007, 2014). "To test this cell-intrinsic role of C3 in pancreatic beta-cells in vivo, we created a beta cell-specific C3KO mouse using a flox/Cre model, and subjected this to a high-fat diet, commonly used as an animal model for human diet-induced obesity." (PMID 41386533, 2026). "The following seven proteins are present in higher amounts in the Obesity group compared with the Control group: hemopexin—HPX, complement factor B—CFB, complement C3—C3, kininogen-1—KNG1, vitronectin—VTN, pigment epithelium-derived factor—SERPINF1 and beta-Ala-His dipeptidase—CNDP1." (PMID 41441338, 2025). "Notably, the elevated complement C3 and α2-MG levels in the obesity and T2DM+obesity groups corresponded with elevated insulin and glucose levels." (PMID 40487757, 2025). "In obesity, serum levels of C3, FB, FH and factor I (FI), but not FD, were elevated when compared to normal weight controls." (PMID 39635529, 2024). "This study showed that when obesity, IR and inflammation parameters were excluded as confounding factors in subjects with PCOS, HDL-associated alpha-1-antitrypsin and complement C3 were still abnormal." (PMID 37181037, 2023). "The serum complement C3 levels are reported to be associated with the severity, risk, and prevalence of NAFLD but not with metabolic syndrome and obesity." (PMID 36143853, 2022). "More recently, circulating C3 levels have been demonstrated to predict the presence of NAFLD in a large cohort from general population independently of the most plausible confounders such as the presence of metabolic syndrome and obesity." (PMID 34395461, 2021). "These peptides were significantly less abundant in high BMI compared to low BMI subjects, whereas a peptide belonging to the complement cascade, complement C3 (CC3, m/z 2172 dysregulated in obesity after Hu7), was more abundant in high BMI compared to low BMI individuals." (PMID 28974732, 2017). "In conclusion, current cross-sectional study in a large Chinese population revealed that serum complement C3 level is positively associated with prevalence and severity of NAFLD, and this association is independent of obesity and metabolic syndrome." (PMID 27029598, 2016). "Serum complement C3 level is positively associated with prevalence and severity of NAFLD, and this association is independent of obesity and metabolic syndrome." (PMID 27029598, 2016). "We observed a significant induction in the levels of C3, CP enzyme, growth factor IGFBP4, and cytokine CXCL10 and interferon signaling-related genes including (IFNβ, ISG15, MX2 and OASL2), some of which have been recognized for their role either in obesity or inflammation." (PMID 33672392, 2021).
Obesity (continued). "Immunodetection of C3 in independent human healthy and obese secretomes from VAT and SAT explants confirmed the oversecretion of C3 by visceral adipose tissue compared to subcutaneous in obesity (p = 0.05) and revealed the elevated secretion of obese VAT in relation to healthy VAT tissue (p = 0.06)." (PMID 26198096, 2015). "Acutely, C3a increases both C3aR and C3, however chronic stimulation with high circulating levels, as in obesity, may lead to negative feedback down-regulation, although the precise mechanism by which this is achieved is unknown." (PMID 24743347, 2014). "Further study has indicated that upregulated alternative CS pathway components, such as C3, properdin, factor B, and factor I, are elevated in non-obese patients with PCOS, which further increases with obesity." (PMID 40904461, 2025). "To explore whether the link between serum complement C3 levels and NAFLD is independent of obesity and metabolic syndrome, we excluded 2383 participants who were obese (BMI ≥ 25 kg/m2) and/or had metabolic syndrome for subgroup analysis." (PMID 27029598, 2016).
nephritis (66 papers, 2009 to 2025). Inflammation of renal tissue. "Between the two, low C3 strongly associates with nephritis and renal damage as reported by Durcan and colleagues." (PMID 40121442, 2025). "Western blotting further showed that the levels of indicators of MC injury such as Tgf-β, Pdgfrb, and Et-1, as well as C3, which can cause damage to MCs in the glomeruli, were increased in the nephritis model group." (PMID 38716725, 2024). "Several authors have reported the association of severe nephritis with low C3; however, disagreement persists over a similar association with low C4." (PMID 36688943, 2023). "In one study in 44 children with IgAN, high serum IgA:C3 ratio together with extensive glomerular C3 staining were associated with persistent kidney inflammation, potentially predicting IgAN progression." (PMID 38106572, 2023). "Surprisingly, measuring serum creatinine or C3 in combination with serum thiols significantly increased the association with nephritis and was able to accurately identify LN type IV patients." (PMID 25799079, 2015). "Moreover, nephritis-associated plasmin receptor (NAPlr), originally isolated from the cytoplasmic fraction of group A Streptococci, is vital as an essential inducer of C3-dominant glomerular injury and is a key diagnostic biomarker for IRGN." (PMID 37176142, 2023). "The previous study comparing patients with SLE reported that those with low levels of both C3 and C4, indicating activation of the classical complement pathway, had higher rates of arthritis, serositis, nephritis, and higher SLEDAI scores." (PMID 41327417, 2025). "and others report that AP in SLE frequently occurs in the setting of active nephritis and low complement levels (C3 and C4), both of which were evident in our patients." (PMID 39582728, 2024). "Of the IgAVN group, nine (60%) had a kidney biopsy with nephritis demonstrated histologically, all of them demonstrated IgA predominant immune deposits and eight (89%) patients had C3 positivity on immunofluorescence." (PMID 38046006, 2023). "A univariate analysis did not identify any significant predictor of flare, including age, race, gender, class of nephritis, and baseline labs (anti-dsDNA antibody, C3, C4, serum creatinine, and UPCR)." (PMID 36874710, 2023). "Upon ROC analysis, C3 and C4 showed a good discriminative ability to detect proliferative nephritis, as demonstrated by AUC (C3 = 0.7841, C4 = 0.7828)." (PMID 36688943, 2023). "In 1969, a C3 splitting factor termed C3Nef was found in patients with a rare form of nephritis characterized by persistent low plasma C3 but normal levels of the early components of the classical pathway." (PMID 36408746, 2023). "As CIC glomerular deposition facilitates inflammation in lupus-like nephritis, we quantified the IgG and complement component C3 deposits in the glomeruli of WT and Lyn−/− mice treated or not with AMG853." (PMID 35444641, 2022). "Although a small proportion of cases with APSGN has been reported to have normal C3 levels, most studies that clearly document the post-Strep A etiology of nephritis have found transient hypocomplementemia to be present in all, or almost all, cases." (PMID 36128411, 2022). "The immune markers Treg percentage, C3, and C4 were definitely lower in nephritis patients compared to non-nephritis patients (p < 0.001) and controls (p < 0.001)." (PMID 34572591, 2021). "Compared with ADSCs, miR-20a-ADSC treatment significantly improved serologic and histologic abnormalities, as evidenced by reduced serum creatinine, anti-dsDNA antibody, 24 h urine protein levels, nephritis scores, and C3/IgG deposits." (PMID 34721589, 2021). "Negative correlations were observed between LRRK2 expression and serum C3 or C4 levels, two clinical features associated with SLE-related nephritis." (PMID 30670047, 2019). "It is well recognized that the decrease in C3 and C4 in the periphery is associated with disease severity of SLE, especially the occurrence of SLE-related nephritis." (PMID 30670047, 2019).
nephritis (continued). "The administration of ARA290 to pristane‐induced SLE and MRL/lpr mice significantly suppressed the level of serum antinuclear autoantibodies (ANAs) and anti‐dsDNA autoantibodies, reduced the deposition of IgG and C3, and ameliorated the nephritis symptoms." (PMID 29570934, 2018). "We found that the administration of ARA290 to pristane‐induced SLE mice and MRL/lpr mice significantly suppressed the level of serum ANAs and anti‐dsDNA autoantibodies, reduced the kidney deposition of IgG and C3, and ameliorated the nephritis symptoms." (PMID 29570934, 2018). "High C4d levels had a statistically superior accuracy as a marker for nephritis than low C4 levels (p = 0.002 by McNemar’s test) and accuracy similar to low C3 levels (p = 0.508)." (PMID 29208014, 2017). "In these studies we utilized a model of TI nephritis in which acute C3 activation in Crry−/−C3−/− kidneys generated C3aR-dependent inflammation." (PMID 24632830, 2014). "In conclusion, in our study we used a model of TI nephritis, in which acute C3 activation leads to C3a generation and deposition of C3b in the TI." (PMID 24632830, 2014). "Immunofluorescence staining of nephritis-associated plasmin receptor (NAPlr) and immunohistological staining of plasmin receptors were stained in an area within the GBM that was different from the area with deposition of C3." (PMID 37452997, 2024). "Our finding of an increase in extrafollicular cells associated with severe disease activity, nephritis, positive Anti-Sm and Anti RNP titers, and decreased C3 could be explained by a possible pathogenetic role of these cells in SLE." (PMID 36148466, 2022). "Besides, miR-20a-ADSC treatment had a stronger repair effect in murine LN compared with the ADSC group, as evidenced by decreased anti-dsDNA antibody, serum creatinine, and 24 h urine protein levels, nephritis scores, and C3/IgG deposits." (PMID 34721589, 2021). "PLS identified sIL-1R4, sIL-1R2 and anti-dsDNA as variables distinguishing patients with active from those with inactive disease; sIL-1R4, IL-18BP and anti-dsDNA identified patients with active nephritis; sIL-1R4, C3, IL-18 and free IL-18 identified patients with haematological involvement." (PMID 29422069, 2018). "This was associated with the detection of complement component C3 and IgG deposits in the kidney glomeruli of pristane-injected mice, unlike the glomeruli of PBS-injected control mice, confirming the early development stages of the pristane-induced lupus-like nephritis." (PMID 35844602, 2022). "Clinical manifestations may vary from microscopic haematuria and/or proteinuria to nephritis, characterized by the deposition of extrarenal-IgA, C3 and other complement factors in the mesangium, subepithelial and subendothelial space, leading to an increased risk of chronic kidney disease." (PMID 34911536, 2021). "The SLEDAI scores and the levels of anti-dsDNA antibodies were also decreased, and the levels of C3 and C4 were increased significantly, although some patients still retained high titers of anti-dsDNA antibodies or hypocomplementemia even after improvement of nephritis." (PMID 26098692, 2015). "Using mass spectrometry, we found an increase in the level of complement components C3, C4b, C5, C9, and CFB in the urine of patients with active nephritis." (PMID 37108355, 2023). "Further evaluation of kidney functions in 10-month-old mice revealed that B6.lpr mice developed severe nephritis, with a decline in kidney function indicated by increased BUN, immune complex deposition, and C3 deposition in B6.lpr mice and." (PMID 36578056, 2022). "Nephritis-related markers (UTP and Scr) and C3 level at recruitment negatively influenced achievement of LLDAS." (PMID 34595670, 2022). "In this pristane-induced lupus-like nephritis, MAR-1-mediated depletion of basophils over a two weeks period of time led to a clearance of C3- and IgG-containing ICs glomerular deposits in the kidney of pristane-injected mice." (PMID 28801578, 2017).
nephritis (continued). "Two had nephritis of which one had biopsy-proven mesangioproliferative GN with absent C1q and C3 on DIF." (PMID 40556690, 2025). "uMCP-1 performed better than serum MCP-1, anti-dsdna antibody, C3, and C4 in ROC analysis to distinguish active nephritis from active disease without nephritis." (PMID 38239353, 2023). "Although C3 has been rarely studied in human anti-GBM disease, the crucial role of complement in pathogenesis has been explored in IgA nephropathy, C3 glomerulonephritis, membranous nephropathy, and other nephritis." (PMID 35874697, 2022). "It is thus not surprising that C4d is a marker for nephritis in the cross-sectional study, but it is noteworthy that it has a better accuracy than C4 and similar accuracy to C3." (PMID 29208014, 2017). "C3−/− kidneys transplanted into wildtype mice and Crry−/−C3−/− kidneys transplanted into Crry−/−C3−/− mice did not develop TI nephritis." (PMID 24632830, 2014). "C3 and C4 levels were significantly lower in patients with nephritis than in patients without nephritis." (PMID 24171081, 2013). "The concentration of urinary complement proteins (C3, C4, C5 and C5a) was evaluated to see if these could distinguish patients with and without nephritis in IgAV." (PMID 36227437, 2023). "Higher frequency and titers of serum autoantibodies to C1q and dsDNA and lower levels of serum of the complement components C3 and C4 were detected in patients with active SLE and active nephritis compared to patients with inactive SLE and without a renal involvement, respectively." (PMID 26549923, 2015).